LEP (leptin)
Diseases named in the same sentence as LEP in open-access papers (continued):
Sharing a sentence is not in itself a finding about the gene and the disease.
lipodystrophy (continued). "Therefore, in cases of lipodystrophy as a consequence of HAART, glitazones are a successful approach, as well as the combination of leptin and glitazones, even though a positive effect on glucose metabolism is not clear." (PMID 33233602, 2020). "Although low levels of leptin are expected during lipodystrophy, leptin assays and reference values have not been well defined for this clinical entity." (PMID 30622652, 2019). "Although BMI has already been positively correlated with leptin levels in lipodystrophy, this correlation is not consistently observed in patients with this disease." (PMID 30622652, 2019). "Thus, the finding of elevated ANGPTL3 levels in patients with lipodystrophy and their reduction following leptin treatment is consistent with the results obtained in leptin deficient mice and suggests that ANGPTL3 may contribute to hypertriglyceridemia in leptin deficient states." (PMID 29752428, 2019). "A recent paper demonstrated that, in lipodystrophy, the metabolic benefits of leptin occurred independent of suppression of food intake." (PMID 30357355, 2019). "Patients with lipodystrophy share some of the clinical manifestations of CLD, due to low/absent blood leptin levels caused by the generalized or partial absence of subcutaneous adipose tissue." (PMID 26881138, 2016). "Follicle-stimulating hormone is involved in the lipodystrophy of adipose tissue; this involvement is further supported by the ability of FSH to alter the levels of two key indicators of lipid droplet formation, namely leptin and ADPN." (PMID 25754247, 2015). "We found that leptin reflected adiposity- and lipodystrophy-related inflammation, but not sarcopenia." (PMID 26244048, 2015). "Our data showed that fat mass/body weight ratio, plasma adiponectin and leptin were significantly decreased in SKO mice due to the lipodystrophy and there was no change in adipose tissue after diet with D/E." (PMID 26690553, 2015). "The adiponectin/leptin ratio was higher in patients with no lipodystrophy and lower in patients with isolated central fat accumulation, followed by the patients with mixed forms of lipodystrophy." (PMID 24958357, 2014). "Recombinant leptin therapy helps improve insulin sensitivity, reduce circulating triglyceride concentrations, and decrease liver volume in patients with lipodystrophy; however, leptin therapy does not adequately address all the metabolic perturbations for reasons that are incompletely understood." (PMID 40663389, 2025). "This reinforces the hypothesis that leptin and GDF-15 act through independent pathways in humans, which is consistent with a study in patients with lipodystrophy and hypoleptinemia, wherein leptin treatment failed to normalize GDF-15 levels." (PMID 38890300, 2024). "Normal or high leptin levels do not rule out a lipodystrophy diagnosis." (PMID 38952397, 2024). "In addition, there are no standardised cut-offs defined for leptin levels to confirm or exclude the diagnosis of lipodystrophy." (PMID 36899861, 2023). "There are no defined serum leptin levels that establish or rule out the diagnosis of lipodystrophy." (PMID 32079542, 2020). "Serum leptin measurement may help clinicians with the management of lipodystrophy, but it should not be considered as a reliable tool to diagnose or rule out lipodystrophy." (PMID 31434462, 2020). "This may explain the lipodystrophy-like phenotype observed in the proband, including her relative lack of lower extremity adiposity and low leptin levels relative to her BMI." (PMID 33210059, 2020). "Although serum leptin levels in patients with lipodystrophy tend to be low (in absolute levels or relative to body mass index), no defined serum leptin level threshold can be used to rule out the diagnosis of lipodystrophy." (PMID 29704234, 2019). "It is not established whether leptin levels are altered in lipodystrophy merely as a result of the AT mass, or whether AT redistribution affects leptin levels." (PMID 26244048, 2015).
lipodystrophy (continued). "Leptin reflected adiposity- and lipodystrophy-related inflammation, but not sarcopenia." (PMID 26244048, 2015). "Adiponectin had been found to promote fat accumulation in adipose tissues and to improve insulin sensitivity in leptin-resistant mice, which could explain the hypoglycemic phenotype of Sik3−/− mice, but not their lipodystrophy." (PMID 22662228, 2012). "In addition, Tsuboyama-Kasaoka, Takahashi, Tnemura, Kim, Tnage, Okuyama, Kasai, Ikemoto, and Ezaki showed preliminary data indicating that leptin infusion lowers the levels of serum insulin and attenuates hepatocyte fat deposition in CLA-fed lipodystrophy model mice." (PMID 18348717, 2008). "Another interesting observation was that leptin therapy led to the attenuation of circulating glucose insulinotropic peptide (GIP) levels and an increase in ghrelin levels in individuals with MASH who had no formal diagnosis of lipodystrophy but relative leptin deficiency." (PMID 40520449, 2025). "However, absence of hypoleptinemia does not rule out lipodystrophy, with one ICI-induced AGL exhibiting significantly increased leptin levels." (PMID 41476924, 2025).
asthma (168 papers, 2006 to 2025). "The aim of our study was to investigate the association of the prognostic role of leptin and adiponectin, as well as the leptin receptor gene polymorphism Gln223Arg, in patients with difficult-to-control and severe asthma." (PMID 40361972, 2025). "Children with asthma tend to have a higher prevalence of IR compared to those without asthma, with IR levels correlating with proinflammatory markers like leptin and IL-6, which are associated with increased airway obstruction and reduced lung volumes." (PMID 40426941, 2025). "On the other hand, higher leptin concentration was associated with asthma in both adults and children." (PMID 40116547, 2025). "Clinical and experimental studies indicate that higher leptin levels are linked to greater airway hyperresponsiveness and more severe asthma phenotypes, potentially through pro-inflammatory signaling and immune modulation." (PMID 40998975, 2025). "in an original study from 2021 analyzed the relationship between leptin and adiponectin and pediatric lung function, specifically assessing the increased risk of developing asthma." (PMID 39371928, 2024). "In particular, several studies found higher levels of leptin and lower levels of adiponectin in association with asthma and a correlation between these hormonal alterations and the severity of respiratory disease, both in adults and in children." (PMID 39371928, 2024). "On the other hand, leptin plays a role in the pro-inflammatory activities, which is closely associated with asthma risk and progression." (PMID 36914629, 2023). "In Brazil, protection against asthma and atopy attributed to variants on the genes for leptin (LEP) and adiponectin (ADIPOQ) were lost in overweight individuals." (PMID 36973960, 2023). "On the other hand, the analysis of the potential role of age and gender in the association between leptin status and asthma also provided a comparatively robust conclusion." (PMID 36914629, 2023). "Studies have shown that leptin plays a crucial role in the development of asthma in obese individuals, as high levels of leptin are associated with asthma." (PMID 37760982, 2023). "The numbers of ILC2 were decreased under the condition of leptin deficiency, ultimately resulting in the alleviation of asthma." (PMID 36551211, 2022). "Several population-based studies in prepubertal children described the association between the presence of asthma and serum leptin levels." (PMID 35889925, 2022). "While few studies have indicated the associations between leptin and M1 macrophages in an obese asthma mouse model." (PMID 36551211, 2022). "In the present study, we explored the general functions and the clinical cohort study supporting the association between leptin and asthma." (PMID 36551211, 2022). "Weight loss was associated with a marked decrease in leptin levels in obese subjects, but it had inconsistent effects in obese asthmatics, possibly reflecting, at least in part, the independent role played by asthma in leptin levels." (PMID 35807067, 2022). "Leptin is implicated in the pathophysiological and cellular mechanisms of the development of asthma." (PMID 36551211, 2022). "Another hormone implicated in this observation is leptin, although there is still a paucity of data concerning the mechanisms involved and the role it plays in airway remodeling in asthma." (PMID 35769576, 2022). "In a logistic regression analysis, rs13228377 polymorphism of leptin and leptin level showed good predictive accuracy, indicating increased asthma risk." (PMID 36551211, 2022). "In a population of 84 obese adolescents, the study showed a reduction in leptin levels and asthma symptoms after weight loss through 1-year therapy." (PMID 36551211, 2022). "Weight loss was reported to reduce circulating leptin concentration and improve the symptoms of asthma." (PMID 36551211, 2022).
asthma (continued). "More recently, it has been published that leptin is not only a risk factor for asthma (OR = 1.06; 95% CI: 0.28–1.31) but that it is positively related with its severity, whilst it is inversely related with the adiponectin levels." (PMID 34836093, 2021). "Leptin was linked to asthma in adults as well as in children; the severity of asthma was correlated to serum leptin levels in a meta-analysis of 13 studies." (PMID 34211985, 2021). "Prenatal chemical exposure and smoking were associated with birth size and growth, cord adiponectin and leptin, thyroid and reproductive hormones, neurodevelopment, and asthma and allergies." (PMID 34022817, 2021). "PRKCA is associated with both BMI and asthma simultaneously, along with other genes with pleiotropic effects like leptin (LEP), and tumor necrosis factor (TNF)." (PMID 33791298, 2021). "Children receiving breast milk with higher levels of leptin and insulin had an increased risk of developing asthma before the age of 3 years." (PMID 35223710, 2021). "Higher leptin levels are believed to be associated with asthma severity, lower lung function and airway hyperreactivity." (PMID 34948451, 2021). "A few cross-sectional studies have reported positive associations of serum leptin concentration with asthma severity, asthma control, lung function, and asthma severity in children and in adults." (PMID 33418879, 2021). "To simplify the role of leptin in the IL-33-induced asthma model, we used leptin-deficient ob/ob mice." (PMID 34074279, 2021). "The study also shows that higher leptin levels were associated with asthma both in adults and children." (PMID 33418879, 2021). "One study found an association between serum leptin levels and asthma control assessed by the Asthma Control Questionnaire (ACQ)." (PMID 33418879, 2021). "Studies have suggested that adipokines, such as leptin and adiponectin, are associated with the development and severity of asthma and mediate the exacerbation of asthma through the regulation of eosinophil survival and trafficking." (PMID 34093643, 2021). "Leptin, a key player in body weight regulation, regulates Th1 responses, and the production of asthma-related proinflammatory mediators is associated with obese females in asthma." (PMID 35096261, 2021). "The results obtained showed that high serum levels of leptin were associated with asthma, and that the association was stronger in women than in men." (PMID 32630168, 2020). "In contrast, obese asthma in adults is associated with increased airway and systemic inflammation, consistent with our observations of increased TNFα, IL-5, IL-33 and leptin concentrations in the BALF of dams fed the high fat diet." (PMID 30700289, 2019). "Risk factors for asthma in children were analyzed, and it was found that BMI, leptin, adiponectin, and blood pressure were identified as risk factors." (PMID 31152468, 2019). "Abdominal adiposity has been linked to higher leptin, which in turn is associated with airway inflammation and greater risk for asthma." (PMID 30964910, 2019). "Recent Meta-analysis studies implicated a positive relationship between serum leptin, which is elevated in obese individuals, and the risk of asthma." (PMID 29891850, 2018). "We found leptin deficiency leads to attenuated asthma symptoms with decreased eosinophilia, and type 2 cytokine production." (PMID 29891850, 2018). "We observed that LEP polymorphism (rs13228377) was associated with higher serum leptin levels in asthma and these two variables had high predictive value for asthma risk (P = 0.007, odds ratio 17.5, predictive accuracy 83.9%)." (PMID 30203371, 2018). "The genotype of rs13228377 LEP polymorphism and serum leptin level significantly increased asthma risk (P = 0.008), showing odds ratio 16.7 and good predictive accuracy (overall 83.9%, in asthma 91.3%, in controls 62.5%)." (PMID 30203371, 2018).
asthma (continued). "Dysregulation of leptin expression by adipose tissue has been shown to influence lung physiology and mechanics, and associates with asthma development." (PMID 29891850, 2018). "Our results suggest that leptin, acting thought its receptor, mediates the association between acetaminophen use and asthma through its involvement in inducing oxidative stress in the lung." (PMID 30231898, 2018). "The main finding of our study is an association of LEP polymorphism and serum leptin level with asthma." (PMID 30203371, 2018). "First, leptin and leptin receptor are expressed in lung tissue and their expression levels have been shown to be associated with asthma development and severity." (PMID 30231898, 2018). "An important finding in our study was the association between leptin and asthma, and specifically in obese asthmatics." (PMID 26770217, 2015). "Previous studies have implicated adiponectin and leptin in the pathogenesis of asthma in obese individuals." (PMID 26610598, 2015). "Leptin levels are higher in women with equivalent BMI when compared to men, and the association between leptin and asthma seems to be stronger in women; both issues support the role of leptin in the pathogenesis of asthma in obese females." (PMID 26538828, 2015). "The increased leptin/adiponectin ratio is also associated with severe asthma compared to mild to moderate asthma." (PMID 26770217, 2015). "Since there are no longitudinal studies examining the association between high serum leptin concentrations and human asthma, the temporal sequence for this association cannot be definitively established." (PMID 24288549, 2013). "A causal role for leptin in asthma is supported by murine studies: the administration of exogenous leptin in leptin-deficient mice augments airway hyperreactivity following allergen challenge, as well as lung inflammation following ozone exposure." (PMID 24066855, 2013). "Studies in human subjects have been mostly limited to associations between circulating or lung levels of leptin and clinical disease outcomes such as asthma prevalence or severity." (PMID 24288549, 2013). "Human data are, however, currently inconclusive regarding the independent association between serum leptin concentration and risk of asthma." (PMID 24066855, 2013). "The results of recent studies are inconclusive regarding the independent association between serum leptin concentrations and the risk for asthma." (PMID 23773659, 2013). "Leptin and adiponectin are two adipokines that are being studied to determine their association with asthma." (PMID 23710195, 2013). "On the other hand, severe asthma exacerbations requiring hospitalization are associated with a transient increase in serum leptin concentrations." (PMID 24288549, 2013). "A relationship between circulating leptin levels and risk of asthma development was observed in females." (PMID 24028436, 2013). "Similar to leptin human data on the independent association between serum adiponectin concentration and asthma are currently inconclusive." (PMID 24454412, 2013). "This is an important limitation of these studies since the US-based study suggests a nonlinear or threshold effect for the highest quartile of serum leptin concentrations on asthma risk." (PMID 24288549, 2013). "Our findings suggest a role of leptin in enhancing neutrophil survival in asthma disease which are associated with altered levels of leptin receptor." (PMID 23383125, 2013). "As was the case for asthma prevalence, the association between serum leptin and asthma severity is less consistent in adults than in children." (PMID 24288549, 2013). "Although still inconclusive, existing data suggest that high serum leptin concentrations are associated with greater asthma severity, particularly among prepubertal boys and peripubertal and postpubertal girls." (PMID 24288549, 2013). "The association between systemic leptin and asthma prevalence is more consistent in clinic-based studies of children than adults." (PMID 24288549, 2013).